NOTCH1 (notch receptor 1)
Diseases named in the same sentence as NOTCH1 in open-access papers (continued):
Sharing a sentence is not in itself a finding about the gene and the disease.
pancreatic cancer (continued). "Therefore, in this study, we investigated the contributions of Notch1 and Notch4 to the development of pancreatic cancer in vivo." (PMID 36970723, 2022). "Finally, our findings showed that MSCs increased SNHG7 expression in pancreatic cancer cells, promoting the stemness and Folfirinox resistance via the Notch1/Jagged1/Hes-1 signaling pathway." (PMID 34631547, 2021). "NOTCH1 phosphorylation was increased in MACC1-AS1-overexpressing pancreatic cancer cells." (PMID 34178644, 2021). "However, both Notch1 and Notch4 have also been described to be highly re-expressed in pancreatic cancer and cholangiocarcinomas." (PMID 33498866, 2021). "In summary, APOL1 could function as an oncogene to promote proliferation and inhibit apoptosis through activating NOTCH1 signaling pathway expression in pancreatic cancer; therefore, it may act as a novel therapeutic target for pancreatic cancer." (PMID 34341330, 2021). "Hence, our findings indicated that SNHG7 interacted with Notch1 to regulate the stemness and Folfirinox resistance in pancreatic cancer." (PMID 34631547, 2021). "Importantly, in this study, our results demonstrated for the first time that USP18-mediated regulation of c-Myc-induced pancreatic cancer cell progression is dependent on Notch1." (PMID 33051403, 2020). "Importantly, we also measured the protein levels of Notch1 in 30 pancreatic cancer tissues with high USP18 expression." (PMID 33051403, 2020). "To test this hypothesis, we first observed whether USP18 and Notch1 directly interact in pancreatic cancer cells, and interestingly, co-IP demonstrated an interaction between USP18 and Notch1." (PMID 33051403, 2020). "Interestingly, this subpopulation expresses high levels of Notch1 and Notch2 compared to other pancreatic cancer cells." (PMID 32796631, 2020). "Moreover, we found that USP18 promoted pancreatic cancer progression via upregulation of Notch-1-dependent c-Myc." (PMID 33051403, 2020). "As we previously observed in different cell lines, a considerable number of tissues present in a high number of patients showed low levels of DYRK2 expression and a high NOTCH1 abundance, from which the differences observed in ovarian, cervical, colorectal or pancreatic cancer stand out." (PMID 31605148, 2020). "First, USP18 and Notch1 directly interact in pancreatic cancer cells." (PMID 33051403, 2020). "Next, to explore whether Notch1 regulates c-Myc in pancreatic cancer cells, we measured the changes in c-Myc expression in Notch1-knockdown BxPC-3 cells." (PMID 33051403, 2020). "Moreover, SNHG1 suppresses pancreatic cancer cell proliferation, invasion and metastasis through inhibiting the Notch-1 signaling pathway." (PMID 31615767, 2019). "In pancreatic carcinomas co-expression of PrPC and Notch1 correlates with poor survival." (PMID 31752162, 2019). "Moreover, western blot analysis suggested the down-regulated expression of Notch-1 in pcDNA3.1-HtrA1 plasmid-transfected pancreatic cancer cells." (PMID 30484491, 2018). "In addition, we found that up-regulation of HtrA1 reduced the expression of Notch-1 in pancreatic cancer cells." (PMID 30484491, 2018). "In addition, we found that overexpression of Notch-1 reversed the suppressive effect of HtrA1 on tumor cell growth, suggesting that the anti-proliferative ability of HtrA1 was dependent on Notch-1 in pancreatic cancer." (PMID 30484491, 2018). "Furthermore, overexpression of Notch-1 abolished the anti-proliferative effect of HtrA1 on pancreatic cancer cells." (PMID 30484491, 2018). "Taken together, our findings demonstrated that HtrA1 could inhibit pancreatic cancer cell growth via regulating Notch-1 expression, which implied that HtrA1 might be developed as a novel molecular target for pancreatic cancer therapy." (PMID 30484491, 2018). "Therefore, our results are consistent with previous findings and suggest the role of AKT signaling in promoting gemcitabine-induced Notch1 activation and pancreatic cancer cell stemness." (PMID 30486896, 2018).
pancreatic cancer (continued). "In addition, down-regulation of Notch-1 suppresses cell growth and induces apoptosis in pancreatic cancer cells." (PMID 30484491, 2018). "Additionally, our in vivo findings demonstrated that pharmaceutical inhibition of Notch1 signaling enhances the killing effect of gemcitabine in pancreatic cancer cells." (PMID 30486896, 2018). "Furthermore, we evaluated if HtrA1 played a role in the regulation of pancreatic cancer cells in a Notch-1-dependent manner." (PMID 30484491, 2018). "This study investigated whether the hypoxic niche enhances gemcitabine-induced stemness and acquired resistance in pancreatic cancer cells by activating the AKT/Notch1 signaling cascade." (PMID 30486896, 2018). "Therefore, our results indicate that miR-34a inhibits pancreatic cancer progression by post-transcriptionally regulating Snail1 and Notch1 expression." (PMID 28145431, 2017). "Furthermore, the anti-apoptotic effects of the miR-34a inhibitors in pancreatic cancer cells were abrogated by Notch1 shRNA." (PMID 28145431, 2017). "Genistein inhibited Notch-1 expression in pancreatic cancer cells." (PMID 28977931, 2017). "This NOTCH1 dependent tumour suppressive effect of LFNG was confirmed in pancreatic cancer supporting that LFNG could be a potential target of specific anti-cancer treatments." (PMID 28603644, 2017). "However, there are also recent reports suggesting that NOTCH1 is overexpressed in patients with colon cancer and that a reduction in NOTCH1 expression induces apoptosis in pancreatic cancer cells." (PMID 28947978, 2017). "Therefore, Quinomycin mediated inhibition of pancreatic cancer growth is partly mediated by inactivating Notch-1." (PMID 26673007, 2016). "Furthermore, the positive regulation of Notch1 level by COX-2 was evident from a siRNA-mediated Ptgs2 (COX-2) knockdown experiment in a pancreas cancer cell line BxPC3 harboring a wild-type K-Ras." (PMID 27381829, 2016). "Additionally, miR-34 family down-regulates Notch1 and Notch2 levels in gastric cancer cells and also inhibits self-renewal of pancreatic cancer stem cells via directly modulating Notch1 and Notch2 receptors." (PMID 26041881, 2015). "However, a disparate viewpoint proposed that Notch-1, as a tumor suppressor in pancreatic cancer, was verified in a model of KRAS-induced PDAC." (PMID 24587996, 2014). "Some studies demonstrated that curcumin might attenuate allergic airway inflammation through NF-κB inhibition and might be a novel therapy for pancreatic cancer through down-regulating the expression of Notch1 and its downstream transcription factor NF-κB." (PMID 24706026, 2014). "Furthermore, in pancreatic cancer cell lines, the inhibition of Notch1 signaling prevents migration and invasion." (PMID 24932308, 2014). "Therefore, we proceeded to a pulse of NOTCH activation by exposing pancreatic cancer NOTCH1-expressing cells to the calcium chelator EGTA." (PMID 24392017, 2013). "Thus, Notch-1 activation plays an important role in the growth of pancreatic cancer cells, and in cell proliferation stimulated by activation of EGFR or PDGFR." (PMID 22479394, 2012). "The role played by NO and Notch-1 in the development of biliary malignancies, as well as pancreatic cancer, is suggested by the evidence that Notch-1 is hyperexpressed both in cholangiocytes of PSC-affects patients and in CC cells where it colocalizes with iNOS." (PMID 21994887, 2012). "Thus, Src and Notch-1 are important proteins affecting pancreatic cancer cell growth, invasion and metastasis." (PMID 22479394, 2012).
pancreatic cancer (continued). "The present study confirmed that the microprotein N1DARP promotes N1ICD degradation by increasing K11- and K48-linked polyubiquitination of N1ICD, suggesting that N1DARP could be a novel therapeutic target for pancreatic cancer that specifically deactivates the Notch1 pathway." (PMID 37714834, 2023). "Moreover, we tried to examine whether SNHG7 modulated stemness and resistance in pancreatic cancer cells through Notch1." (PMID 34631547, 2021). "Therefore, we deduced that Notch1 was a target for SNHG7 in pancreatic cancer." (PMID 34631547, 2021). "In conclusion, these findings may provide novel insight into the cancer-promoting effects of USP18 and its potential clinical application in pancreatic cancer, which suggests that the USP18/Notch1/c-Myc pathway may act as a crucial regulator of pancreatic cancer progression." (PMID 33051403, 2020). "Therefore, we investigated whether aberrant expression of Notch1 or Snail1 could affect miR-34a expression levels in pancreatic cancer cells." (PMID 28145431, 2017). "However, it remains unknown whether the Notch1 gene is a target of miR-34a or whether overexpression of Notch1 regulates miR-34a in pancreatic cancer." (PMID 28145431, 2017). "Moreover, PDGF-D promotes tumorigenesis and aggressiveness by activating Notch1 pathway in breast and pancreatic cancers, but it is unclear whether this also occurs in CRC." (PMID 28035069, 2017). "Similarly, downregulation of Notch1 contributes to cell growth inhibition in pancreatic cancer." (PMID 24512546, 2014). "In pancreatic cancer, APOL1 was found to promote inhibit apoptosis and cell proliferation via the regulation of NOTCH1 signaling, confirming its role as an oncogene." (PMID 40649778, 2025). "In the current study, the chemosensitivity of pancreatic cancer cells to gemcitabine has been enhanced using a single and combination of ANGTPL4, Notch1 and NF-κβ1 siRNA." (PMID 38817387, 2024). "Upon reintroduction of miR-34 into pancreatic cancer cells through either using miR-34 mimics to transfect or through lentiviral MiR-34-MIF infection, a decrease of Bcl-2 and Notch1/2 occurred." (PMID 38725047, 2024). "While silencing Notch1 results in the inhibition of cell proliferation, reduction of ALDH+ cell, and induction of apoptosis and gemcitabine resistance in pancreatic cancer." (PMID 37409635, 2023). "The activation of Notch 1 is also known to induce EMT markers, ZEB1 and Snail-1 in pancreatic cancer cells." (PMID 36685076, 2023). "Considering the possible roles of Notch1 in cancer, NUMB is promised to exhibit the inhibitory potential for tumor progression and has been clarified in lung cancer and pancreatic cancer." (PMID 37760477, 2023). "In breast and pancreatic cancer, there was an increase in the expression levels of JAG1, JAG2, Notch1, Notch3, and Hes1, a downstream gene of Notch signaling." (PMID 36226253, 2022). "Moreover, Notch 1 expression has been related to cisplatin resistance in different types of cancers, such as head and neck squamous cell carcinoma and colon carcinoma, and Notch 3 expression has been related to gemcitabine resistance in pancreatic cancer cells." (PMID 33916610, 2021). "AKT1, CDKN2A, ERBB2, and IL6 are common protein core of liver and pancreatic cancers, while STAT3, CASP3, NOTCH1, and CTNNB1 are possible differential proteins to discriminate these cancers." (PMID 35154607, 2021). "GHET1 promotes prostate cancer progression through targeting KLF2 which activates the HIF-1alpha/NOTCH-1 pathway, and MACC1-AS1 drives pancreatic cancer progression through activating PAX8/NOTCH1 signaling." (PMID 34703793, 2021). "STAT3 and CASP3 were determined as specific hub nodes related to liver cancer, while NOTCH1 and CTNNB1 were characterized as the specific hubs of pancreatic cancer." (PMID 35154607, 2021). "STAT3 and CASP3 were dysregulated in liver cancer; however, NOTCH1 and CTNNB1 were related to pancreatic cancer." (PMID 35154607, 2021).
pancreatic cancer (continued). "The current results indicate that AKT1, CDKN2A, ERBB2, and IL6 are the common protein core of liver and pancreatic cancers, and STAT3, CASP3, NOTCH1, and CTNNB1 are possible differential proteins that discriminate these cancers." (PMID 35154607, 2021). "Our results suggest a potentially adverse collaboration between Notch1 and AKT, in which the two signaling pathways are intertwined in increasing the stemness of pancreatic cancer cells upon gemcitabine chemotherapy." (PMID 30486896, 2018). "The reduction of Notch1 levels after treatment in CCA is consistent with our previous data on hepatocellular carcinoma and pancreatic cancer." (PMID 29152142, 2017). "Here, we showed that miR-34a regulates both Notch1 and the EMT activator Snail1 at the post-transcriptional level, which affects pancreatic cancer cell processes." (PMID 28145431, 2017). "For example, Notch1 over-expression induces EMT by increasing the expression of Vimentin and N-cadherin in pancreatic cancer." (PMID 28035069, 2017). "KMC14 cells expressed mRNA of Notch-1, Notch-2, Jagged-1, c-Met, CXCR-4, CD24 and CD44, except Jagged-2, that were reported as pancreatic cancer markers." (PMID 24278411, 2013). "Human pancreatic CSCs expressing high levels of CD133, CD24, CD44, ESA, and aldehyde dehydrogenase also express significantly more Nanog, Oct-4, Notch1, MDR1 and ABCG2 than normal pancreatic tissues and primary pancreatic cancer cells." (PMID 21304978, 2011). "Normal pancreatic tissues express very low levels of CD133, CD24, CD44, ESA, Nanog, Notch1, MDR1 and ABCG2 compared to pancreatic cancer and CSCs." (PMID 21304978, 2011). "Our data showed that the expression of Bcl-2, Bcl-xL, Notch-1, and survivin proteins was significantly induced in response to CXCL12 treatment of pancreatic cancer cells." (PMID 21045835, 2010). "Restoration of miR-34 expression in the pancreatic cancer cells by either transfection of miR-34 mimics or infection with lentiviral miR-34-MIF downregulated Bcl-2 and Notch1/2." (PMID 19714243, 2009). "High-throughput approaches such as chromatin immunoprecipitation sequencing (ChIP-seq) have demonstrated that NOTCH1 and NOTCH2 exhibit distinct chromatin binding profiles in pancreatic cancer cell lines (e.g., BXPC3), suggesting functional divergence and target gene specificity." (PMID 41200204, 2025). "Taken together, these findings confirm that N1DARP acts as a tumor suppressor and chemosensitizer by regulating USP10-Notch1 oncogenic signaling, and suggest a promising therapeutic strategy targeting the N1DARP–N1ICD interaction in Notch1-activated pancreatic cancer." (PMID 37714834, 2023). "Additionally, the restoration of miR-34 in human pancreatic cancer BxPC3 and MiaPaCa2 cells induces apoptosis and enhances sensitivity to GEM by inhibiting the expression of Notch1, Notch2, and Bcl-2." (PMID 38139352, 2023). "First, TQ may have enhanced the sensitivity of the pancreatic cancer cells to GEM by inhibiting the neurogenic gene Notch homolog protein 1/phosphorase and tensin homolog (Notch1/PTEN) pathway." (PMID 36686732, 2022). "Triptonide exerts anti-cancer effects through down-regulation of various oncogenic genes, including β-catenin, cMyc, Notch1, LXRα, SREBF1, particularly, triptonide directly binds to its receptor LXRα, reduces LXRα protein stability in pancreatic cancer cells, and exerts potent anti-cancer effect." (PMID 34922602, 2021). "Besides, leptin is reported to induce the expression of Notch1-4, JAG1 and DLL4 in pancreatic cancer cells." (PMID 34588926, 2021). "We demonstrated that Notch1 interacted with SNHG7 and could reverse the facilitative effect of SNHG7 on the stemness and Folfirinox resistance in pancreatic cancer cells." (PMID 34631547, 2021).
pancreatic cancer (continued). "The increased expression of Notch1 and 3 in PDAC tissues was observed, suggesting that both of these receptors may play an important role in the development of pancreatic cancer, and researchers have therefore referred to these receptors as oncogenes." (PMID 33670230, 2021). "Conversely, overexpression of NOTCH1 increased the expression of oncogenic miR-21 while decreasing the expression of miR-200b, miR-200c, let-7a, let-7b and let-7c, promoting EMT and a CSC-like phenotype in pancreatic cancer cells." (PMID 34572067, 2021). "Notch1 is one of the Notch transmembrane receptors; despite several studies carried out on mice describe both its tumor-suppressor and oncogenic function in pancreatic cancer, the activation of Notch1 is not sufficient to induce tumorigenesis." (PMID 33266496, 2020). "In addition, metformin also upregulates let-7 family, miR-200 family, miR-101 and Oct4, Notch-1, and EZH2 mRNAs in pancreatic cancer cells." (PMID 32512882, 2020). "We provide evidence that combination treatment with adjuvant drugs targeting such signaling pathways offers a better therapeutic benefit against pancreatic cancer in vitro and in vivo, suggesting AKT/Notch1 as attractive targets for eliminating pancreatic CSCs." (PMID 30486896, 2018). "Notch-1 signaling is an important pathway to upregulate the expression of EMT markers, ZEB1 and 2, Slug and vimentin, leading to the EMT, migration and drug resistance of pancreatic cancer cells." (PMID 27231938, 2016). "We next addressed whether the MEK/ERK pathway could influence NOTCH signalling particularly in our pancreatic cancer cell model MIA PaCa-2, which displays basal NOTCH1 activation/NIC1 expression but inducible NOTCH1 activation." (PMID 24392017, 2013). "To see whether systemic therapy with PP2 could affect the Notch-1-c-Src interaction in xenograft tumors in vivo, we established HPAC human pancreatic cancer xenografts in nude mice." (PMID 22479394, 2012). "Consequently, SELN, like exosomes expressed by pancreatic cancer cells, in part exosomes expressed by SOJ-6 cells affected the functioning of the Notch-1 survival pathway." (PMID 23094054, 2012). "We next examined the expression of stem cell markers (CD133+CD44+CD24+ESA+), pluripotency maintaining factors (Nanog), signaling molecule (Notch-1) and drug resistant genes (MDR1 and ABCG2) in human normal pancreas, primary pancreatic cancer cells, and CSCs by q-RT-PCR." (PMID 21304978, 2011). "Targeting the N1DARP–N1ICD interaction and N1ICD degradation could be a promising alternative strategy for treating Notch1-activated pancreatic cancer and may have broader applications in the treatment of non-cancerous diseases." (PMID 37714834, 2023). "Altogether, these imply that C5EOSEW5050ESA may confer gemcitabine-resistant pancreatic cancer cells to necrotic cell death through the blockade of the Notch signalling pathway by downregulating Notch1 ICD, HES-1, and HEY-2 to potentiate gemcitabine sensitivity in resistant pancreatic cancer cells." (PMID 36685076, 2023). "The expressions of the Notch1/Jagged1/Hes-1 signaling pathway components (Notch1, Jagged1, and Hes1) in PANC-1 and AsPC-1 cells were examined by qRT-PCR and Western blot tests to assess the biological relevance of SNHG7 in pancreatic cancer stemness and Folfirinox resistance." (PMID 34631547, 2021). "In a pulldown test, SNHG7 could only pull down Notch1 rather than antisense SNHG7 in pancreatic cancer cells, showing that SNHG7 interacted with Notch1." (PMID 34631547, 2021). "Indeed, Notch1 status represents a negative predictive biomarker of gemcitabine treatment and prognosis in pancreatic cancer patients." (PMID 33266496, 2020). "However, the regulatory mechanisms of the Notch1-c-Myc signalling pathway in pancreatic cancer is still not clear." (PMID 33051403, 2020).